CAT (catalase)
Diseases named in the same sentence as CAT in open-access papers (continued):
Sharing a sentence is not in itself a finding about the gene and the disease.
diabetes (continued). "Catalase is the second most abundant enzymatic antioxidant (after SOD), which attenuates the levels of ROS that ubiquitously accompany pathological disorders such as aging, cataract, cancer, atherosclerosis, and diabetes." (PMID 32911700, 2020). "A relationship between this new classification of diabetes with catalase expression levels or its activity has still not been probed for a link, if any, and needs further research." (PMID 31827713, 2019). "Administration of agmatine to animals with DM significantly increased SOD, CAT, GPx and GR activities 2.27-fold, 1.3-fold, 43 % and 72 %, respectively, in comparison to the non-treated diabetes group." (PMID 33817163, 2019). "Diabetes induction altered neither the gene expressions of catalase mRNA level, a cytosolic H2O2 scavenger, nor SOD2, a mitochondrial superoxide detoxifier." (PMID 31690052, 2019). "In addition, bixin and norbixin increased antioxidant enzymes activity in animal models of diabetes and atherosclerosis, while bixin upregulated gene expression of SOD and CAT in a mouse model of diabetic cardiomyopathy." (PMID 30944740, 2019). "Lack of catalase can contribute to the development of diabetes mellitus with a positive correlation being observed between diabetes mellitus in acatalasemic patients." (PMID 31827713, 2019). "In addition, streptozotocin-induced diabetes also significantly decreases GSH and glutathione-s-transferase and CAT; TQ reverses these changes." (PMID 29743967, 2018). "Inside the diabetic heart, catalase activity was suppressed while immunofluorescence for angiotensin receptor AT1 was significantly high (p<0.05), suggesting suppression of antioxidant enzymes and activation angiotensin system activation in diabetes." (PMID 29206854, 2017). "Although, some studies determining activities of CAT and SOD in DM exhibited the depletion in the activity of these enzymes, other studies reported the increment in the activity of both enzymes with the STZ-induced diabetes." (PMID 26753525, 2016). "In diabetes, both hyperglycemia and oxidation of glucose produce large amounts of free radicals, resulting in increased activity and expressions levels of antioxidant enzymes, including GPX, catalase, and SOD." (PMID 27929393, 2016). "Also important is that upregulation of HO-1 activity can resist diabetes-induced oxidative stress by increasing SOD and catalase activity." (PMID 26845693, 2016). "Furthermore, induction of diabetes using STZ in rats attenuated the activities of the antioxidant enzymes in the testicular tissues including SOD, CAT, GR and GPx." (PMID 27869771, 2016). "Furthermore, the alteration of the activities of the antioxidant enzymes such as CAT and SOD has also been reported in different types of cataract, including diabetic cataract." (PMID 26821002, 2016). "In the present study of a relatively large Chinese population, we found that patients with diabetes had a significant increase in plasma MDA and a significant decrease in plasma TAC and CAT activity, erythrocyte SOD and GPx activity, and erythrocyte GSH content." (PMID 26204833, 2015). "Numerous studies have identified significant alterations in plasma antioxidant vitamins (including vitamins C, E and A), antioxidant enzyme systems [superoxide dismutase (SOD), catalase (CAT) and glutathione peroxidase (GSH-Px)] and in lipid peroxidation in diabetes." (PMID 25574229, 2015). "Induction of diabetes led to increased hepatic level of cholesterol, triglyceride (TG), low density lipoprotein (LDL), and lipid peroxidation and decreased activities of glutathione (GSH), catalase (CAT), and superoxide dismutase (SOD) and HDL level." (PMID 26713163, 2015). "The data of our study also revealed that daily treatment of saffron extract markedly improves antioxidant status of the hippocampus tissue of rats with streptozotocin-induced diabetes as GSH level and antioxidant enzymes activities comprising SOD and CAT significantly increased." (PMID 25114929, 2014).
diabetes (continued). "The chronic effect of the diabetes led to the upregulation of superoxide dismutase (SOD) and catalase (CAT) activities, and the downregulation of glutathione peroxidase (GPx), but there was no statistically significant increase in the malondialdehyde (MDA) levels." (PMID 24982856, 2013). "Diabetic kidneys had increased transcript and membrane-bound protein levels of Nox4, the renal-specific generator of cytosolic reactive oxygen species (ROS) and reduced expression of SOD2, UCP2, GPX3, NQO1, and CAT." (PMID 23149823, 2013). "During diabetes, there was a significant reduction in the activities of SOD, CAT and GPx." (PMID 20931083, 2010). "The increased ROS levels in diabetes could be due to their increased production and/or decreased destruction by antioxidants such as GSH, SOD, catalase and glutathione peroxidase." (PMID 20630072, 2010). "In diabetes, the activities ofantioxidant defense enzymes responsible for scavenging freeradicals and maintaining redox homeostasis such as SOD,glutathione reductase, glutathione peroxidase, and catalase arediminished in the retina." (PMID 17641741, 2007). "These markers include the enzymatic activities of catalase, SOD, GSH-Px, and GSH-reductase, as well as thiobarbituric acid reactants (TBARS) levels, an indirect measurement of free-radical production that has been shown to be consistently elevated in diabetes." (PMID 15862133, 2005). "CAT activity increased in nondiabetes nonpregnant women (2.06 ± 1.86 mU/l) but decreased nonsignificantly (p > 0.05) in gestational diabetes (1.29 ± 0.56 mU/l), normal pregnant (1.28 ± 0.70 mU/l), and diabetes (1.20 ± 1.03 mU/l) women." (PMID 41013820, 2025). "Since the levels of catalase were not changed in the diabetic heart with or without treatment, it is likely that the modification of oxidative stress biomarkers by diabetes, as well as due to insulin or sarpogrelate treatment, is site-specific in the oxidative stress pathway." (PMID 39057635, 2024). "Treatment of streptozotocin-induced animal model of diabetes with safranal (0.25, 0.50, and 0.75 mg/kg/day, IP for 4 weeks) reduced MDA, NO, and glutathione (GSH) contents but increased the activities of SOD and CAT in the BALF and lung tissue of diabetic rats." (PMID 38629099, 2024). "Likewise, MG demonstrated the ability to prevent renal injury in diabetes-bearing mice by repressing ROS and malondialdehyde (MDA) levels, while enhancing the production and secretion of defensive proteins like GSH, SOD, and catalase (CAT)." (PMID 38542669, 2024). "In the context of diabetes treatment, insulin is known to possess additional anti-inflammatory effects, including the activation of the Nrf2 signaling pathway, which promotes the expression of antioxidant enzymes like total SOD, catalase (CAT), and glutathione peroxidase." (PMID 38550920, 2024). "In the streptomycin-induced diabetes mouse, the extracts significantly reduced glucose levels in the blood and increased antioxidant enzyme activity (SOD, CAT, GSHPX), but not only glycosylated serum proteins, but also antioxidative enzyme activity (SOD, CAT, GSHPX)." (PMID 36877269, 2023). "In experimentally induced diabetes mellitus (DM), folic acid administration lowers glycemia and improves the activity of specific enzymes, including superoxide dismutase (SOD) and catalase (CAT)." (PMID 38201117, 2023). "Furthermore, blood CAT and NO concentrations were not affected by diabetes, but increased by supplementation with RA combined with a high dose of L-arginine or a high dose of Cr(III), probably in response to increased metabolic stress." (PMID 36297315, 2022). "However, the source of the oxidant is unclear and the administration of catalase in the previous study did not affect the diabetes-induced coronary endothelial dysfunction in response to serotonin." (PMID 36613929, 2022).
diabetes (continued). "Therefore, we hypothesized that both MSCs and Q/Zn improve diabetes-induced pancreatic complications, possibly by up regulating the expression of SOD and CAT mRNAs." (PMID 33661932, 2021). "Finally, diabetes induction or subsequent treatment with crocin did not affect catalase gene expression in the liver." (PMID 32161725, 2020). "Induction of diabetes by HFD and STZ resulted in a disturbance in oxidative stress parameters in the serum of the rats as compared to the rats from the non-diabetic group C. In the DM2 rats there was a significant increase in the SOD and CAT activities as well as in the TBARS level." (PMID 31771099, 2019). "Diabetes did not change expression of Nox1 or catalase in mesenteric arteries." (PMID 32009974, 2019). "It was found that there has been a significant decrease in the activity of antioxidant enzymes, including SOD, CAT, GPX, and GR, with the reduction of GSH content in all tissues of diabetic rats, whereas the level of MDA has increased, which indicates oxidative stress in diabetes." (PMID 30944708, 2019). "Increased reactive oxygen species (ROS) levels in diabetes may be due to decreased destruction and/or increased production of catalase (CAT--enzymatic/non-enzymatic), superoxide dismutase (SOD) and glutathione peroxidase (GSH–Px) antioxidants." (PMID 28975089, 2017). "Interestingly, diabetes-induced suppression of PMP70 and catalase were reversed by APX-115 or losartan in the kidneys, suggesting that APX-115 could also regulate peroxisomal biogenesis in diabetic kidneys." (PMID 29088780, 2017). "However, to the best of our knowledge, none of the previous researches investigated the biological variations of antioxidant enzymes (CAT, CuZnSOD) and MDA in urines of healthy individuals as well as in urines of patients with diabetic nephropathy (DN) and type 2 diabetes mellitus (T2DM)." (PMID 25649751, 2015). "It is noteworthy that, although transgene expression of antioxidant enzymes such as MnSOD and catalase were shown to reduce oxidative stress in beta cells of mice, these enzymes did not confer protection against cytokine-mediated cytotoxicity in the MLDS model of diabetes." (PMID 26422139, 2015). "The results here and previous data indicate that blood CAT activities are not altered by diabetes." (PMID 26064423, 2015). "In addition, in a parallel investigation with a similar experimental protocol, we demonstrated that MLT had effective antioxidant action in this gland under diabetes by equilibrating glutathione S-transferase (GST), catalase, and glutathione peroxidase (GPx) activities." (PMID 26295055, 2015). "Studies examining catalase activity in CKD are contradictory, but catalase might reflect antioxidant status in diabetes, rather than CKD." (PMID 24058721, 2013). "Interestingly, neither diabetes nor exercise training altered plasma SOD activity whereas plasma CAT activity was significantly increased in response to exercise training (TR/DB), approximately 45%, as compared with C/SD and SD/DB." (PMID 23285277, 2012). "Results showed that salidroside possessed hypoglycemic activity and protective effects against diabetes-induced oxidative stress, which could significantly reduce FBG, TC, TG and MDA levels, and at same time increase serum insulin levels, SOD, GPx and CAT activities." (PMID 22134398, 2011). "Whereas ozone therapy in control rats produced no significant changes in kidney tissue SOD, CAT and GPx activity levels, induction of diabetes in group D produced significant decreases in the activity levels of the three enzymes when compared with control rats (group C)." (PMID 20465785, 2010). "Moreover, disturbances of antioxidant defense systems in diabetes showed alteration in antioxidant enzyme levels, such as superoxide dismutase (SOD), catalase (CAT), glutathione peroxidase (GPx) and glutathione reductase (GR) along with impaired glutathione (GSH) metabolism." (PMID 20376213, 2009).
diabetes (continued). "For example, in the heart, which is an important target in diabetes and prone to diabetic cardiomyopathy leading to chronic heart failure, SOD and glutathione peroxidase expression as well as activity are decreased whereas catalase is increased in experimental models of diabetes." (PMID 15862133, 2005). "Additionally, CAT and SOD1 genes/proteins are assumed to highly influence the control of the PPI network because these are also known as antioxidative enzymes having a very potent role in diabetes and diabetes-related complications including diabetic nephropathy." (PMID 34367469, 2021). "In diabetes, OS may occur due to auto-oxidation of glucose, shifts in redox balances, decreased tissue concentrations of low molecular weight antioxidants, such as reduced glutathione (GSH) and impaired activities of antioxidant defense enzymes such as SOD, CAT, and increase MDA level in the body." (PMID 27199747, 2016). "In conclusion, our findings illustrate that the animal model of diabetes induced by alloxan did not cause alterations in the animals' recognition memory, but it produced oxidants and an imbalance between SOD and CAT activities, which could contribute to the pathophysiology of diabetes." (PMID 22645603, 2012). "There was a statistically significant difference in CAT activity between the groups with DN, DMT2N1 (p = 0.004) and DMT2N2 (p = 0.002), and patients with diabetes without complications, DMT2N0 (CAT), compared to controls." (PMID 41011276, 2025). "Some of the studies support the conclusion that GSH-Px, CAT and SOD levels are not different from control group in diabetes studies while the others advocate that GSH-Px, CAT and SOD levels are different from control group in diabetes studies." (PMID 27275196, 2015). "It is well known that people with diabetes have a lower antioxidant defense, enzymatic (SOD, catalase and GPx) and non-enzymatic (vitamin C, E or A, free radical scavengers)." (PMID 25561939, 2015). "The least was observed in NSK and HBP + M (4.7 ± 6.65, 4.82 ± 0.41), while a significant difference (P < 0.05) was observed in CAT levels for HBP + M, TRB, and NSK (177.92 ± 107.8, 106.75 ± 7.18, 76.25 ± 21.57) when compared to the person with the diabetes-induced infection without treatment." (PMID 36312784, 2022). "Diabetes-induced reduction of CAT and increase of SOD1 protein levels in rat kidney tissue were normalized by resveratrol toward the control values, whereas down-regulated mRNA levels of CAT, GPx and SOD1 were not affected by resveratrol treatment." (PMID 33803588, 2021). "Our result showed a significant decrease in the levels of catalase, SOD, and GST in serum and kidney tissue homogenate of the positive control group (G2) compared with that of the negative control group (G1) as a result of induction of diabetes." (PMID 27525022, 2016).
Obesity (136 papers, 2011 to 2026). Accumulation of substantial excess body fat. "In previous studies, the SNPs SOD2 rs4880, GPX7 rs835337, GPX1 rs1050450, and CAT rs1001179 have been associated with lipid peroxidation, obesity, and their metabolic complications in adult populations." (PMID 40867795, 2025). "In the association analysis that was adjusted for age and sex, obesity was positively associated with the enzyme activity of CAT (β = 0.05 ± 0.01, p = 5.0 × 10−3) and GPx (β = 0.13 ± 0.01, p = 3.7 × 10−19)." (PMID 38671905, 2024). "Studies on erythrocytes report the possible correlation of single nucleotide polymorphisms (promoter variant -844A/G) and post-translational modifications of CAT with the risk of developing obesity and its comorbidities." (PMID 39176098, 2024). "In conclusion, in Mexican children, obesity is positively associated with CAT and GPx enzyme activity, and its associations with MDA levels and SOD enzyme activity are sex-specific." (PMID 38671905, 2024). "Our results for Mexican children evidence that obesity is associated with an increase in CAT and GPx enzyme activity and that its associations with lipid peroxidation and SOD enzyme activity are sex-specific." (PMID 38671905, 2024). "Obesity resulted in being positively associated with CAT (β = 0.05 ± 0.01, p = 5.0 × 10−3) and GPx (β = 0.13 ± 0.01, p = 3.7 × 10−19) enzyme activity." (PMID 38671905, 2024). "The positive associations between obesity and the enzyme activity of CAT and GPx that we evidenced in this study are consistent with previous reports." (PMID 38671905, 2024). "Under this scenario, proteins are expected to suffer from glycosylation, although we recently found children with obesity and IR to have decreased rates of catalase O-GlcNAcylation, a reaction that is mediated by O-linked N-acetylglucosamine transferase (OGT)." (PMID 37672200, 2023). "Cafeteria diet consumption has been associated with obesity and oxidative stress in experimental animal by alteration in the catalase, SOD, glutathione, and MDA levels." (PMID 34122598, 2021). "In this study, we investigated the involvement of excessive H2O2 in the development of obesity, taking advantage of catalase-knockout (CKO) mice, and the underlying molecular mechanisms." (PMID 33080438, 2020). "CAT is associated with obesity or insulin resistance, and it is a decomposing enzyme from H2O2 to O2 and H2O, resulting in oxidative stress plays an important role in the development of MetS." (PMID 31171927, 2019). "Cardiac oxidative stress and increased catalase levels are closely linked to increased fat metabolism associated with high-fat diet and obesity." (PMID 24950187, 2014). "Due to this fact, our group recently published a study conducted on obese children that showed the association of some SNPs located in the CAT promoter with obesity." (PMID 24562334, 2014). "In our prior study, we show that reactive oxygen species (ROS) generation via CoCl2 or IL-6 treatment enhances this TET1 pathway and ROS neutralization via catalase represses this pathway, potentially explaining the inflammatory hallmark of clinical obesity as a risk factor for TNBC." (PMID 37231419, 2023). "L. Inodorus) prevents obesity, protects against hyperlipidemia, improves cardiac risk indices, catalase activities, protein level, nitrate concentration and reduces oxidative stress that could result from consumption of a high-fat diet." (PMID 36539762, 2022). "Finally, we have shown that the compound 3-AT can be successfully used to inhibit CAT activity in adipocytes in vitro as a tool for the study of ROS in metabolic alterations associated with obesity." (PMID 27023799, 2016). "However, increased abundance of CAT, together with other proteins related to metabolic pathways has been associated with human AT protection and insulin-stimulated glucose uptake improvements in obesity." (PMID 38703299, 2024).